PPEF1 (protein phosphatase with EF-hand domain 1)
Description:
May have a role in the recovery or adaptation response of photoreceptors (By similarity).
Synonyms: PPEF; PP7; PPP7C; PPP7CA
Tractability: No criterion of Open Targets' tractability assessment is met for any kind of drug.
Target class: Enzyme; Hydrolase
Gene: Protein-coding gene on chromosome X (18,675,909 to 18,827,921, forward strand). Ensembl gene ENSG00000086717.
Subcellular location (Human Protein Atlas): Plasma membrane; Cytokinetic bridge
Pathways (Reactome):
Sensory Perception: Inactivation, recovery and regulation of the phototransduction cascade
Gene Ontology:
Molecular function: protein binding; protein serine/threonine phosphatase activity; calcium ion binding; hydrolase activity; iron ion binding; manganese ion binding; phosphoprotein phosphatase activity
Biological process: positive regulation of proteasomal protein catabolic process; detection of stimulus involved in sensory perception
Cellular component: cytosol
Homologues: Orthologues: chimpanzee PPEF1 (97% identical), macaque PPEF1 (95% identical), dog PPEF1 (78% identical), pig PPEF1 (76% identical), rabbit PPEF1 (71% identical), rat Ppef1 (71% identical), guinea pig PPEF1 (70% identical), mouse Ppef1 (69% identical), tropical clawed frog ppef1 (54% identical), zebrafish ppef1 (52% identical), Caenorhabditis elegans pef-1 (40% identical), Drosophila melanogaster rdgC (39% identical), and 28 more. Paralogues in human: PPEF2 (49% identical), PPP5C (22% identical), PPP3CB (19% identical), PPP3CA (19% identical), PPP3CC (18% identical), PPP1CB (16% identical), PPP1CC (16% identical), PPP1CA (16% identical), PPP2CA (16% identical), PPP2CB (16% identical), PPP4C (15% identical), PPP6C (14% identical).
Diseases named in the same sentence as PPEF1 in open-access papers:
PPEF1 is named in the same sentence as 15 diseases in open-access papers, as found by Europe PMC text mining. Sharing a sentence is not in itself a finding about the gene and the disease. The quoted sentences say what the papers report.
breast carcinoma (3 papers, 2019 to 2022). "Along with being an unfavorable prognostic marker, PPEF1 is negatively associated with OS and metastasis-free survival of breast cancer." (PMID 35874675, 2022). "We found that the PPPCs family had high diagnostic accuracy for breast cancer, with PPP1CA, PPP4C and PPEF1 having the highest diagnostic accuracy." (PMID 34964699, 2022). "With these results, we suggest for the first time that the DEGs of the PPPCs family, except for PPP2CA and PPEF1, lead to reduced infiltration of immune cells in breast cancer tissues, which can affect the development and immunotherapy of breast cancer." (PMID 34964699, 2022). "Except for PPP1CB, PPP1CC, PPP5C and PPEF1, the mRNA expression levels of the PPPCs family in breast cancer tissues were significantly different from those in paracancerous tissues." (PMID 34964699, 2022). "In the Oncomine database, when compared with normal breast tissues, PPP1CA, PPP2CA, PPP4C and PPEF1 were significantly elevated in breast cancer tissues, while PPP1CB, PPP2CB, PPP3CA, PPP3CB, PPP3CC and PPP6C were significantly decreased in breast cancer tissues." (PMID 34964699, 2022).
lung carcinoma (2 papers, 2017 to 2021). "To investigate the functional role of PPEF-1 in genotoxic stress-induced apoptosis, we performed MTT and TUNEL assays in A549 lung cancer cells after overexpression of wild-type PPEF-1 or inactive PPEF-1D172N mutant." (PMID 28051100, 2017). "Collectively, these data demonstrate that PPEF-1 plays a pivotal role in tumorigenesis of lung cancer cells by reducing PDCD5-mediated genotoxic stress responses." (PMID 28051100, 2017). "Our data from the in vivo xenograft assay indicate that PPEF-1 overexpression increased the tumorigenic growth and chemoresistance of A549 cells, suggesting that PPEF-1 can act as an oncogene in lung cancer development by preventing cancer cell death." (PMID 28051100, 2017). "We also determined that overexpression of wild-type PPEF-1, but not inactive PPEF-1D172N, significantly increased tumorigenic growth and chemoresistance of A549 human lung carcinoma cells." (PMID 28051100, 2017).
colorectal cancer (1 paper, 2017). A primary or metastatic malignant neoplasm that affects the colon or rectum.
pancreatic adenocarcinoma (1 paper, 2021). "In addition, PPEF1 showed low expression in both pancreatic adenocarcinoma and normal tissues." (PMID 33270085, 2021). "PPEF1 and PPEF2 showed low expression in both pancreatic adenocarcinoma and normal tissues in this work." (PMID 33270085, 2021).
pancreatic cancer (1 paper, 2021). "A trend was seen in PPP1CA, PPP1CB, and PPEF1: they were also overexpressed in pancreatic cancer, with fold changes between 1.5 and 2.0." (PMID 33270085, 2021). "However, we found that PPEF2, rather than PPEF1, demonstrated a favorable prognostic value at the mRNA level in pancreatic cancer." (PMID 33270085, 2021).
tumor (5 papers, 2016 to 2023). "Our results suggested that the four mRNA vaccine targets, namely, ADAMTS18, COL10A1, PPEF1, and STRA6, were positively correlated with the infiltration of dendritic cell, thereby activating cytotoxic T cells against tumor cells." (PMID 35874675, 2022). "POSTN, PPEF1, SAMSN1 and TNFSF13B were upregulated in a great majority of the ccRCC tumours." (PMID 27358011, 2016). "Moreover, the presence of “anti-cancer” next to “pro-tumorigenic” within a single tumor only complicates the final conclusion regarding AP-2 role in that cancer (e.g. KRT14 vs GRIA1, SEZ6L, SLC12A5 for AP-2α within PAAD or NTSR1 vs PPEF1 for AP-2γ within LUAD)." (PMID 35361846, 2022).
cancer (4 papers, 2017 to 2023). A tumor composed of atypical neoplastic, often pleomorphic cells that invade other tissues. "Further elucidation of PPEF-1 function in human cancer tumorigenesis will facilitate the development of targeted therapeutics for cancer treatment." (PMID 28051100, 2017). "ET treatment increased DNA damage and cancer cell death, whereas PPEF-1 overexpression dramatically suppressed the ET-induced DNA damage response and cell death." (PMID 28051100, 2017).
PPEF1 also shares sentences with these, for which no sentence is quoted: infection (2 papers); cyst (1); end-stage renal failure (1); hepatocellular carcinoma (1); malignant pheochromocytomas (1); retinal degeneration (1); Sepsis (1); type 2 diabetes (1).